TRBV19 (T cell receptor beta variable 19)
Description:
V region of the variable domain of T cell receptor (TR) beta chain that participates in the antigen recognition. Alpha-beta T cell receptors are antigen specific receptors which are essential to the immune response and are present on the cell surface of T lymphocytes. Recognize peptide-major histocompatibility (MH) (pMH) complexes that are displayed by antigen presenting cells (APC), a prerequisite for efficient T cell adaptive immunity against pathogens. Binding of alpha-beta TR to pMH complex initiates TR-CD3 clustering on the cell surface and intracellular activation of LCK that phosphorylates the ITAM motifs of CD3G, CD3D, CD3E and CD247 enabling the recruitment of ZAP70. In turn ZAP70 phosphorylates LAT, which recruits numerous signaling molecules to form the LAT signalosome. The LAT signalosome propagates signal branching to three major signaling pathways, the calcium, the mitogen-activated protein kinase (MAPK) kinase and the nuclear factor NF-kappa-B (NF-kB) pathways, leading to the mobilization of transcription factors that are critical for gene expression and essential for T cell growth and differentiation. The T cell repertoire is generated in the thymus, by V-(D)-J rearrangement. This repertoire is then shaped by intrathymic selection events to generate a peripheral T cell pool of self-MH restricted, non-autoaggressive T cells. Post-thymic interaction of alpha-beta TR with the pMH complexes shapes TR structural and functional avidity.
Synonyms: TCRBV17S1A1T; TCRBV19S1
Gene: T-cell receptor variable (V) gene on chromosome 7 (142,618,849 to 142,619,532, forward strand). Ensembl gene ENSG00000211746.
Subcellular location: Cell membrane
Gene Ontology:
Biological process: cell surface receptor signaling pathway
Cellular component: alpha-beta T cell receptor complex; plasma membrane
Homologues: Orthologues: macaque TRBV19 (81% identical), pig TRBV19 (75% identical), guinea pig TRBV19 (69% identical), dog TRBV19 (68% identical), mouse Trbv19 (67% identical). Paralogues in human: TRBV28 (54% identical), TRBV27 (53% identical), TRBV10-3 (52% identical), TRBV6-1 (52% identical), TRBV10-2 (51% identical), TRBV6-2 (51% identical), TRBV6-7 (51% identical), TRBV6-8 (51% identical), TRBV10-1 (50% identical), TRBV6-4 (50% identical), TRBV6-5 (50% identical), TRBV6-6 (50% identical), and 39 more.
Diseases named in the same sentence as TRBV19 in open-access papers:
TRBV19 is named in the same sentence as 6 diseases in open-access papers, as found by Europe PMC text mining. Sharing a sentence is not in itself a finding about the gene and the disease. The quoted sentences say what the papers report.
influenza (3 papers, 2010 to 2020). An acute viral infection of the respiratory tract, occurring in isolated cases, in epidemics, or in pandemics; it is caused by serologically different strains of viruses (influenzaviruses) designated A, B, and C, has a 3-day incubation period, and usually lasts for 3 to 10 days. "Cluster 2 revealed influenza specific memory cells, expressing TRBV19, known to code for a public TCR specific to the highly-conserved M158–66 immunodominant epitope." (PMID 32070336, 2020). "Importantly, these TRAV27/TRBV19 TCRs display the key motifs for A2+M158 epitope recognition, similar to those found in adults, tissues, and influenza-infected patients." (PMID 29997621, 2018). "A detailed mutational analysis revealed that germline-encoded residues were critical for antigen specificity and, along with CDR3β Arg peg, it was hypothesized that the TRBV19 gene may have been evolutionary useful during recurrent influenza pandemics." (PMID 21124993, 2010).
contact dermatitis (1 paper, 2021). An inflammatory skin condition caused by direct contact between the skin and either an irritating substance or an allergen. "In this study, we showed several highly expanded T cell clones by sequencing data, and demonstrated the preferential usage of TRBV19, TRBV5-1, and TRBV20-1, consistent with previous studies on Ni2+ contact dermatitis." (PMID 33670995, 2021).
melanoma (1 paper, 2009). A malignant, usually aggressive tumor composed of atypical, neoplastic melanocytes. "Conversely, other authors reported that the recognition of melanoma Ags involved the use of T lymphocytes bearing specific TRBV chains, such TRBV5, TRBV9, TRBV19, TRBV27, and TRBV28." (PMID 19317896, 2009).
infection (1 paper, 2022). The state of being infected such as from the introduction of a foreign agent such as serum, vaccine, antigenic substance or organism. "Quantifying and visualizing the number of cells using a given germline pairing revealed certain V genes dominated the repertoire across multiple mice in different infection conditions, such as TRBV13-1, TRBV19, and TRBV29." (PMID 35185882, 2022).
TRBV19 also shares sentences with these, for which no sentence is quoted: COVID-19 (1 paper); tumor (1).